VDR (vitamin D receptor)
Diseases named in the same sentence as VDR in open-access papers (continued):
Sharing a sentence is not in itself a finding about the gene and the disease.
diabetes (continued). "However, based on the number of studied patients in this region, it seems that a general panel of NOS, TCF7L2, VDR, and PON1 polymorphisms can be used as diagnostic panel markers to identify the susceptible cases to diabetes in Middle East population." (PMID 35366956, 2022). "The gene-enrichment analysis of the diabetes-associated expressed genes revealed that a significant number of these genes were correlated with T-cell antigen receptor (TCR) pathway, vitamin D receptor pathway, toll-like receptor signaling, and ER unfolded protein response." (PMID 36360783, 2022). "Numerous studies demonstrated that vitamin D/VDR was involved in the regulation of diabetes, chronic kidney disease, pulmonary fibrosis, chronic inflammation, and fibrosis of cardiovascular disease, along with the occurrence and development of many liver diseases." (PMID 35043727, 2022). "Interestingly, VDR knockout NOD mice presented an unaltered presentation of diabetes compared to VDR+/+ mice." (PMID 35625724, 2022). "For example, Oh, JY, and Barrett-Connor, E found that the bb genotype of BsmI VDR polymorphism was associated with insulin resistance after adjustment for age, sex, BMI, and Ca and vitamin D use in a Caucasian population without diabetes." (PMID 35684100, 2022). "To date, only one study in the central region of Malaysia has explored the association between the VDR BsmI (rs1544410) polymorphism and vitamin D deficiency, obesity, and insulin resistance among participants without diabetes across different age groups." (PMID 33567588, 2021). "Accordingly, our findings showed that neither VDR (FokI and BsmI) genotype was significantly associated with diabetes risk among the Malaysian population." (PMID 33567588, 2021). "Evidence that may explain the underlying mechanism is decreased glucose consumption in the skeletal muscle and the presence of vitamin D receptor and 1-alpha hydroxylase activity in the pancreas of diabetes patients." (PMID 33728195, 2021). "Moreover, detection of vitamin D receptors (VDR) on β cells has supported the role of 25(OH)D in the pathogenesis of diabetes." (PMID 33801988, 2021). "Cinacalcet users were slightly younger, included more patients with chronic glomerulonephritis and fewer patients with diabetes, were more likely to have a history of parathyroidectomy, and were more often used receiving vitamin D receptor activator, phosphate binders, and iron supplements." (PMID 31141505, 2019). "Hence, in the current study, we stratified the study participants according to their Hp genotype and their diabetes status and explored the involvement of the iron-klotho-VDR axis in the renal PCT injury." (PMID 30250850, 2018). "Moreover, vitamin D receptor knockout mice were unexpectedly protected from low-dose streptozotocin–induced diabetes mellitus and EAE was less severe in VDR null mice." (PMID 28390010, 2017). "In a group of young T1DM patients and we found higher frequency of VDR FokI polymorphism in individuals with thyroid auto antibodies without relation to age and duration of diabetes." (PMID 27011770, 2016). "The activated VDR regulates approximately 3% of all genes and may protect against diabetes by regulating insulin secretion and resistance and by reducing inflammatory damage to the pancreatic islets." (PMID 26699871, 2015). "VDR is the key nuclear receptor for the active hormonal form of vitamin D [1,25-dihydroxyvitamin D3, 1,25(OH)2D3] and there is some previous evidence for its role in obesity- and diabetes- related traits." (PMID 24641809, 2014). "However, other studies examined VDR SNPHAP in relation to diabetes(types 1 and 2), insulin resistance and cardiovascular outcomes." (PMID 25191583, 2013). "Regarding VDR ApaI polymorphisms, older adults without diabetes that have aa genotype had higher fasting plasma glucose and prevalence of glucose intolerance than those with AA genotype." (PMID 22347618, 2012).
diabetes (continued). "The relationship between VDR gene polymorphisms (Bsm-I, Apa-I and Fok-I) and target organ damage with essential hypertension was explored in 74 patients without types 2 diabetes mellitus or impaired glucose tolerance and severe obesity." (PMID 23049672, 2011). "There was evidence that VDR genotype modified relations of diabetes with change in ROI volumes." (PMID 22028967, 2011). "Deregulation of VDR function may lead to several diseases such as diabetes." (PMID 39408904, 2024). "They found that at least four different genetic factors or VDR modifications may have a role in the development of type 2 diabetes mellitus: alteration of calcium metabolism, modification of adipocyte activity, modification of insulin secretion, and modification of cytokine production." (PMID 36407246, 2022). "In the context of type 2 diabetes mellitus pathophysiology, it has been reported that vitamin D may exhibit some actions in pancreatic beta cells such as activation of the VDR; and binding of 1,25(OH)2D to the VDR, which promotes transcription of regulated genes to its active form." (PMID 35276762, 2022). "Nevertheless, our results suggested that the BsmI polymorphism was associated with insulin resistance among participants with T2DM who had poor glycemic control and that the VDR FokI polymorphism was associated with obesity risk among participants without diabetes." (PMID 33567588, 2021). "Furthermore, we noticed significant associations between the VDR 2228570 C > T (FokI) polymorphism and risk of obesity among healthy participants without diabetes." (PMID 33567588, 2021). "Therefore, our aim was to investigate how T1D changes tissue distribution of CYP27B1 and VDR and whether vitamin D3 (cholecalciferol) treatment can affect diabetes-related dysfunction of the vitamin D-endo/para/autocrine system." (PMID 29552033, 2018). "Thus, the role of the VDR and its individual variations, instead of the serum concentration of vitamin D metabolites per se might be important in the pathogenesis of diabetes, myocardial infarction (MI), cancer, and mortality." (PMID 26699871, 2015). "In light of these novel human results translated from animal experiments, we hypothesize that activation of the VDR represents a method to lower renal-vascular tissue-RAS activity in human diabetes, and could therefore play an important role in the primary prevention of diabetic nephropathy." (PMID 23971740, 2013). "The VALIDATE-D study is the first human intervention study to evaluate whether direct VDR activation can lower the human RAS in diabetes, compared to the effect of an ACE inhibitor, and whether this mechanism can translate to clinically relevant endpoints for diabetic kidney disease." (PMID 23971740, 2013). "The results of the VALIDATE-D study will shed light on: 1) the mechanism by which VDR activation influences renal-vascular function in human diabetes (via modulation of the RAS), and 2) whether VDR activation modulates renal hemodynamics and proteinuria in human diabetes." (PMID 23971740, 2013). "Consequently, we conclude that the 1,25(OH)2D3/VDR-mediated increase in TCF-4 may have a protective role in colon cancer as well as diabetes and Crohn's disease." (PMID 19924301, 2009). "Activation of other NRs such as vitamin D receptor (VDR) and liver X receptor (LXR) is also shown to be protective in various disease conditions such as cardiovascular disease, diabetes, and neurodegenerative diseases by modulating ER stress." (PMID 38609183, 2024). "Suppression of Pin1, through gene silencing, Juglone treatment, Vitamin D receptor (VDR) agonists, or bromocriptine-QR, alleviates chronic oxidative stress and vascular dysfunction induced by diabetes." (PMID 38711994, 2024). "This study found that nerve regeneration following corneal injury is significantly delayed by diabetes, VDD, and VDR KO, with compounded delays found in diabetic VDD and VDR KO mice." (PMID 38136625, 2023).
diabetes (continued). "Previous studies have shown that vitamin D (its bioactive form 1α,25(OH)2D3) and the vitamin D receptor (VDR) are involved in the development of T2D, suggesting a potential therapeutic role for vitamin D in diabetes 5-8." (PMID 37908738, 2023). "Furthermore, no VDR polymorphisms interacted significantly with 25(OH)D for diabetes." (PMID 37845735, 2023). "Combined VDR activation and RAAS inhibition resulted in synergistic effects in mouse models for both type 1 and type 2 diabetes mellitus." (PMID 35054991, 2022). "Hence, any variations in the VDR gene could affect the insulin level and might lead to diabetes." (PMID 32823649, 2020). "The PBAF-BRD7 and BAF-BRD9 complexes participate in the maintenance and survival of pancreatic β cells through their interaction with the vitamin D receptor (VDR), which has been shown to contribute to the development of diabetes when defective." (PMID 32992509, 2020). "Cholecalciferol treatment significantly attenuated the harmful effect of diabetes on CYP27B1 and VDR expression in hepatic tissue, which additionally supports the association of these changes with the reduced vitamin D bioavailability." (PMID 29552033, 2018). "The administration of cholecalciferol partially or completely abrogated the effects of diabetes on CYP27B1 and VDR expression in the kidneys." (PMID 29552033, 2018). "Our results are consistent with the reports of previous studies that the expression of PPARα, VDR, and FXR was downregulated by the induction of diabetes." (PMID 24465611, 2014). "The selective vitamin D receptor (VDR) activator, paricalcitol, effectively reduces proteinuria in patients with type 2 diabetes mellitus (T2DM) who have been treated with RAAS inhibitors." (PMID 23209764, 2012). "Supporting this hypothesis, the current study demonstrated that 24,25 Vit D increases corneal wound healing times in diabetic VDD and VDR KO mice." (PMID 37509101, 2023). "Mice with the vitamin D receptor (VDR) null phenotype have higher incidence rates of diabetes, suggesting that the vitamin D pathway may be relevant to the pathogenesis of diabetes." (PMID 29672520, 2018). "Animal studies have elegantly shown that activating the VDR results in lowering of the renal-vascular tissue-RAS, and that this interaction translates to reduced kidney injury, particularly in the setting of animal models of diabetes." (PMID 23971740, 2013). "The VALIDATE-D study will extend these findings by employing a double-blinded randomization, employing direct VDR agonist therapy, and focusing on patients with diabetes without CKD." (PMID 23971740, 2013). "However, the physiological relationship between the levels of vitamin D and VDR expression and wound healing in diabetes have not been fully understood." (PMID 36829206, 2023). "In this regard, the study design is optimized to decipher the individual role of VDR activation, and the effect of combining VDR activation with conventional RAS inhibition, since this combination therapy has been shown to provide synergistic renoprotection in animal models of diabetes." (PMID 23971740, 2013). "In order to verify whether the increase of VDR expression in podocytes could enhance the renoprotective effect of VD, some researchers compared the therapeutic effectiveness of low-dose VD analogs doxercalciferol (Dox) in STZ-induced wild-type (WT) diabetes and VDR-overexpression mice." (PMID 32766307, 2020). "Nevertheless, the recent discovery of ample distribution of vitamin D receptors (VDR) in non-skeletal tissues dramatically increased the interest in this vitamin as a therapeutic modality for the prevention of chronic diseases, such as obesity and Type 2 diabetes mellitus (T2DM)." (PMID 24747593, 2014). "Here, the overexpression of VDR and CYP27B1 induced by M. tuberculosis infection was not affected by high glucose concentrations, suggesting a possibility for vitamin D supplementation in patients with diabetes mellitus and TB." (PMID 35204769, 2022).
diabetes (continued). "VALIDATE-D is the first human study to investigate whether vitamin D therapy to activate the VDR can lower circulating and renal-vascular tissue-RAS activity in diabetics without CKD." (PMID 23971740, 2013).
Obesity (163 papers, 2008 to 2026). Accumulation of substantial excess body fat. "Several polymorphisms of the vitamin D receptor exist, such as TaqI (rs731236), although their association with obesity remains inconsistent." (PMID 42213218, 2026). "In obesity, a risk haplotype was associated with increased expression of inflammasome components, upregulation of proinflammatory cytokines, and reduced VDR expression." (PMID 40076474, 2025). "The purpose of our study was to investigate the association between two single-nucleotide polymorphisms (SNPs) (Apal, rs7975232, and Taql, rs731236) of the VDR gene and the risk of obesity in the Bangladeshi population." (PMID 41264635, 2025). "VDR activation exhibits strong anti-inflammatory effects in mouse hepatic macrophages, including those isolated from diet-induced obesity livers, and mice with genetic loss of VDR developed spontaneous hepatic inflammation at 6 months of age." (PMID 40728969, 2025). "No study has investigated the association of ApaI and TaqI polymorphisms of the VDR gene with obesity in the Bangladeshi population." (PMID 41264635, 2025). "In contrast, VDR mRNA levels in adipose tissues are higher in obesity and positively associated with inflammatory makers, suggesting that vitamin D metabolism and actions in adipose tissues are altered in obesity." (PMID 39940444, 2025). "Genotyping more SNPs is warranted to find the putative polymorphisms of the VDR gene that increase the risk of obesity." (PMID 41264635, 2025). "Multiple studies have reported an association between several genetic variants of the VDR gene with obesity but the results have been contradictory." (PMID 41264635, 2025). "The aim of our study was to evaluate the association between VDR gene polymorphism ApaI (rs7975232, C > A) and TaqI (rs731236, T > C) with the risk of obesity in the Bangladeshi population." (PMID 41264635, 2025). "Studies demonstrate that VDR deficiency promotes spontaneous chronic liver inflammation and hepatic steatosis, whereas VDR activation mitigates fatty acid and cholesterol accumulation in obesity-associated models." (PMID 40514735, 2025). "Lower vitamin D levels and VDR gene polymorphisms are also associated with susceptibility to obesity." (PMID 40557234, 2025). "Overall, the association between TaqI VDR polymorphism and obesity or T2DM is still under investigation, and further research is required to fully understand the relationship." (PMID 39328465, 2024). "In fact, several studies have comprehensively cataloged the association of specific VDR gene variants with health impediments like obesity, T2DM, PCOS, and CVD, which also serve as predisposing factors for GDM [29,]." (PMID 38882352, 2024). "The combined effects of obesity and VDR gene polymorphisms on susceptibility to type 2 diabetes mellitus (T2DM) have been explored." (PMID 39328465, 2024). "Increased susceptibility to obesity has also been shown by some researchers for the rs1544410 and rs731236 variants in the VDR gene." (PMID 39458556, 2024). "This study represents a valuable step in investigating the potential link between VDR BsmI and obesity susceptibility." (PMID 39045947, 2024). "Genetic variation within the VDR gene is a significant factor, associated with anthropometric characteristics in obesity in a central European population." (PMID 39458556, 2024). "They suggested that Brazilian T2DM patients presented lower 25(OH)D serum levels unrelated to obesity and VDR polymorphisms." (PMID 36839157, 2023). "In general, the genetic expression and polymorphism of VD and VDR can be used as a genetic marker for predisposition, diagnosis, prognosis, and progression of obesity." (PMID 37848505, 2023). "The majority of these results depend on variations in the VDR gene, which has been linked to obesity features in some studies." (PMID 37351236, 2023). "We therefore measured how gene expression was impacted by either deficient serum vitamin D3 levels or obesity and enriched for VDR cistrome genes." (PMID 37082578, 2023).